SNAI2 (snail family transcriptional repressor 2)
Diseases named in the same sentence as SNAI2 in open-access papers (continued):
Sharing a sentence is not in itself a finding about the gene and the disease.
ovarian carcinoma (continued). "In the detachment section, BACH1 is also involved in the invasive progression of ovarian cancer at the peritoneal surface owing to its effect on EMT genes such as Snail family transcriptional repressor 2 (Slug)." (PMID 32780245, 2020). "It has previously been shown that miR-509-3p mimics also suppressed expression of GPC6 and other transcripts (e.g., SNAI2 and TWIST) associated with EMT in ovarian cancer cell lines." (PMID 31199813, 2019). "In this study, we have reported the negative regulation of SNAI1 on SNAI2 expression in ovarian cancer via the recruitment of the histone deacetylase (HDAC) corepressor to the proximal E-box binding sites." (PMID 31165775, 2019). "Overexpressed PTAF induced elevated SNAI2 expression by competitively binding to miR-25, which in turn promoted ovarian cancer cells epithelial-to-mesenchymal transition (EMT) and invasion." (PMID 30691465, 2019). "We previously demonstrated that miR-203 is a tumor suppressor miRNA in ovarian cancer and that miR-203 expression inhibits tumor growth by targeting transcription factor Snai2." (PMID 30241553, 2018). "We previously reported that miR-203 functions as a tumor suppressor in ovarian cancer cells by directly targeting transcription factor Snai2 and inhibiting epithelial to mesenchymal transition (EMT), whereas BIRC5/survivin promotes EMT." (PMID 30241553, 2018). "This study also emphasizes the potential and importance of SNAI2 in promoting lymphovascular spread of ovarian cancer." (PMID 28039463, 2017). "Our findings also emphasizes the potential of SNAI2 in promoting lymphovascular spread of ovarian cancer." (PMID 28039463, 2017). "Previous results showed that SNAI2 increased the motile and invasive ability of ovarian cancer cells." (PMID 28039463, 2017). "The aberrant expression of SNAI2 and advanced stage are independent risk factors for the LVSI presence in ovarian cancer." (PMID 28039463, 2017). "Slug is the product of the SNAI2 gene and is overexpressed in numerous cancers, including leukemia, esophageal cancer, lung cancer, breast cancer, ovarian cancer, prostate cancer, and colorectal cancer." (PMID 20565806, 2010). "SNAI2 (also known as Slug) is a zinc-finger transcription factor that plays a key role in cancer onset, progression and metastasis, and an increased expression has been reported in several cancers, including ovarian cancer." (PMID 38203758, 2024). "So, SNAI2 knockdown may induce ferroptosis and inhibit the progression of ovarian cancer by downregulating SLC7A11." (PMID 36438923, 2022). "Taken together, erastin could suppress tumor growth of ovarian cancer, which was partly diminished by SNAI2 overexpression, suggesting that SNAI2 might exert tumor-promoting activity by regulating ferroptosis." (PMID 35220872, 2022). "The role of SNAI2 knockdown resembled to erastin in ovarian cancer." (PMID 35220872, 2022). "Considering the importance of SLC7A11 and GPX4 in ferroptosis, we speculated that SNAI2 might be involved in the regulation of ferroptosis, which accounted for its role in ovarian cancer." (PMID 35220872, 2022). "suggest that SNAI2’s non-canonical signaling pathway causes EMT in ovarian cancer cells by decreasing miR-222-3p transcription and upregulating PDCD10 expression." (PMID 36591476, 2022). "Furthermore, the anti-tumor and pro-ferroptosis effects of erastin on ovarian cancer in vivo were partially weakened by SNAI2 overexpression, further verifying the critical role of SNAI2-mediated ferroptosis in ovarian cancer progression." (PMID 35220872, 2022). "This functional role of SNAI2 might facilitate the extravasation of ovarian cancer cells into surrounding tissues, for example, the capillary lumens of lymphovascular system." (PMID 28039463, 2017).
ovarian carcinoma (continued). "The prognostic significance of SNAI2 expression and other clinicopathological variables was first assessed by univariate Cox, followed by multivariate Cox regression analysis regarding to the overall survival time in a cohort of 160 ovarian cancer patients." (PMID 29041931, 2017). "However, the analogy to breast and ovarian cancer suggests that SNAI2/SLUG is an ER responsive gene in lung cancer as well." (PMID 25928859, 2015). "Furthermore, miR-506, which regulates another E-cadherin repressor, SNAI2, is also downregulated in ovarian carcinoma." (PMID 24677166, 2014). "Therefore, we speculated that EPYC in ovarian cancer might regulate the expression of SNAI2 by activating the TGF-β/PI3K/AKT signaling pathway, and promoted the occurrence of EMT and invasion and metastasis of ovarian cancer." (PMID 34888227, 2021). "Jin and colleagues reported that an increased SNAI2 expression and ferroptosis were observed in SKOV3, A2780 and CAOV3 ovarian cancer cells compared to normal human ovarian surface epithelial (OSE) cells." (PMID 38203758, 2024). "DAB2 expression had significant positive correlations with mesenchymal markers (ZEB2, TGFβ1, SNAI2, ZEB1, FN1, MMP2, TWIST1 and MMP3) and CSC markers (CD44 and MYD88) in ovarian cancer cell lines (CCLE) and tissues (TCGA: RNA sequencing and microarray)." (PMID 37815603, 2023). "However, the potential mechanism between ferroptosis and SNAI2 in ovarian cancer remains unclear." (PMID 36438923, 2022). "In ovarian cancer cells, SNAI2 expression is upregulated by PTAF via sponging miR-25, which suppresses SNAI2 expression via direct binding to its 3′UTR." (PMID 35736633, 2022). "Moreover, SNAI2 could directly bind to SLC7A11 promoter and regulate SLC7A11 expression, which might be the potential mechanism underlying SNAI2-regulated ferroptosis in ovarian cancer." (PMID 35220872, 2022). "SNAI2 is directly activated by BACH1 in PDAC, ovarian cancer, and esophageal squamous cell carcinoma cells, suggesting that the BACH1–SNAI2 axis likely contributes to the silencing of epithelial genes." (PMID 34339740, 2021). "CXCR7 overexpression not only significantly enhances histone modification and transcription, but also indirectly induces the expression of mesenchymal markers such as SNAI1, SNAI2, and CDH2 to promote migration and invasion of ovarian cancer cells." (PMID 33829065, 2021). "Among which, SNAI1 and SNAI2 were efficiently induced during EMT and their expressions were correlated with poor clinical outcome in patients with breast, colon and ovarian carcinoma." (PMID 31165775, 2019). "By using an in-house panel of ovarian cancer cell lines, SGOCL, we firstly investigated the SNAI1 and SNAI2 mRNA expression and protein abundance." (PMID 31165775, 2019). "In an ovarian cancer cell lines panel, we identified that SNAI1 and SNAI2 expressions were mutually exclusive, where SNAI1 predominantly represses SNAI2 expression." (PMID 31165775, 2019). "miR-506, miR-382, miR-7, and miR-106 inhibit EMT by directly targeting Snai2, receptor tyrosine kinase orphan receptor 1 (ROR1), EGFR, and ZEB1/2 in ovarian cancer cells, respectively." (PMID 30241553, 2018). "Meanwhile, we try to explore the potential link between SNAI1, SNAI2, and LVSI status in ovarian cancer using data from The Cancer Genome Atlas (TCGA) database." (PMID 28039463, 2017). "Thus, SNAI2 can inhibit ferroptosis by blocking SLC7A11 expression and can therefore promote ovarian cancer progression." (PMID 38203758, 2024). "SNAI2/Slug, and SNAI1/Snail have been reported to be upregulated by treatment with TGF-β and BMP as well as by treating ovarian cancer cells with IL-17, chemokine CCL5, and CCL19/CXCR7." (PMID 36766756, 2023). "In addition, SNAI2-3ʹ untranslated regions (UTR) cloud promote the invasion of ovarian cancer cells, further emphasizing the tumor-promoting action of SNAI2 in ovarian cancer." (PMID 35220872, 2022).
ovarian carcinoma (continued). "A human normal ovarian cell line IOSE-80 and four ovarian cancer cell lines (SKOV3, A2780 and CAOV3) were applied to detect SNAI2 and ferrptosis level, and an elevated SNAI2 expression and the occurrence of ferroptosis were observed in ovarian cancer cells, especially in SKOV3 cells." (PMID 35220872, 2022). "Taken together, the results suggested that SNAI2 knockdown could promote ferroptosis in SKOV3 cells, likely accounting for its inhibitory effect on cell migration and invasion abilities in ovarian cancer." (PMID 35220872, 2022). "The results from qRT-PCR and Western blot assays showed that both the mRNA level and protein expression of SNAI2, SLC7A11 and GPX4 in SKOV3, A2780 and CAOV3 cells were higher than that in IOSE-80, suggesting that SNAI2, SLC7A11 and GPX4 were upregulated in ovarian cancer." (PMID 35220872, 2022). "Our previous study showed that ovarian cancer cells induced to have mesenchymal phenotype either by overexpression of EMT transcription factors (ZEB1, SNAI1, and SNAI2), oncogenes (H-Ras v12), or by drug resistance were all consistently more deformable than cells with epithelial phenotype." (PMID 33330495, 2020). "To further investigate the mechanism by which C17orf91 elicited its oncogenic role, we explored whether C17orf91 could regulate key pro-metastatic genes, such as KLF8, MYC, SNAI2, TWIST1, ZEB1 and ZEB2 in ovarian cancer." (PMID 27535740, 2016). "EMT was induced by hypoxia in a variety of tumors including non-small cell lung cancer (NSCLC) and ovarian carcinoma, and the mechanism involves the regulation of SNAIL, twist family bHLH transcription factor (TWIST) and snail family transcriptional repressor 2 (SLUG)." (PMID 33499904, 2021). "In addition, important cellular modulators, such as non-coding RNAs, Ets-1, CEBPG, ARID1A, SNAI2 and HRD1, could significantly regulate SLC7A11 expression in ovarian cancer cells, suggesting that these modulators could be potential therapeutic targets in ovarian cancer patients." (PMID 38203758, 2024). "Many of the other EMT-related transcription factors, such as SNAI2, TWIST1, and ZEB1 are often overexpressed in the MAF signature, but SNAI1 is not (and, at least in ovarian carcinoma in which we have methylation data, this is due to its differentially methylated status)." (PMID 21047417, 2010).
prostate carcinoma (61 papers, 2011 to 2025). A carcinoma that arises from epithelial cells of the prostate gland. "Perhaps the best example thus far is SNAI2, encoding the transcription factor Slug that is directly associated with the invasive potential of prostate cancer cells." (PMID 32296610, 2020). "In our study, we analyzed the association of CDK4, TWIST1, and SNAI2 single gene expression with the prognosis of prostate cancer patients in the GSE21032 dataset taken from the SurvExpress database." (PMID 31060254, 2019). "Alike ZEB1 also SNAI1 and SNAI2 are strongly associated with high Gleason score 10, indicating them as markers of an aggressive and advanced prostate cancer phenotype." (PMID 29206234, 2017). "We have previously shown that ERβ2 increased expression of EMT-associated genes Twist1 and Slug (SNAI2) in prostate cancer cells." (PMID 26010887, 2015). "Moreover, EMT-related transcription factors (EMT-TFs), such as TWIST1 (Twist), SNAI1 (Snail), and SNAI2 (Slug) were all required for migration/metastasis and the alteration of these factors was associated with advanced prostate cancer." (PMID 31060254, 2019). "In prostate cancer, it induces snail family transcriptional repressor 2 (SLUG) and cyclin D1, promoting invasion and proliferation." (PMID 40361374, 2025). "According to research, SNAI2 epigenetic silencing governs dynamic variations in SNAI2 expression, and restoring SNAI2 expression with panobinostat improves dasatinib sensitivity, indicating a new therapeutic strategy for prostate cancer." (PMID 37251370, 2023). "Here, the authors define, for the first time, the distinct clinical relevance of SNAI2 expression at different disease stages of prostate cancer (PC)." (PMID 34792282, 2022). "We demonstrate that, even though snail family transcriptional repressor 2 (SNAI2) is frequently amplified in prostate cancer, it is epigenetically silenced in this disease, with dynamic changes in SNAI2 levels showing distinct clinical relevance." (PMID 34792282, 2022). "A target gene of AR which is important for repression of prostate cancer progression is Snail Family Transcriptional Repressor 2 (SNAI2), yet its expression is repressed by enzalutamide-treatment induced GR expression." (PMID 31771198, 2019). "CDK4, TWIST1, and SNAI2 three-genes were selected based on the significant expression profiles of these genes, and prognostic relevance of these genes for prostate cancer patients." (PMID 31060254, 2019). "Fourth, GA-mediated the expression of one pro-proliferative cell cycle regulator (CDK4) and two EMT-TFs (TWIST1 and SNAI2) of prostate cancer cells can act as a marker of GA exposure." (PMID 31060254, 2019). "miR-203 has been reported to be downregulated in prostate cancer and associated with cancer metastasis by targeting BMI1, LASP1, ZEB2 and SNAI2." (PMID 29552304, 2018). "In the present study, we demonstrate that PCAT3 and PCAT9 regulates tumorigenesis, migration, angiogenesis, stemness and metastasis in prostate cancer via modulating the miR-203/SNAI2 axis." (PMID 29552304, 2018). "In DU145 prostate cancer cells, over-expression of SNAI2 increases drug resistance to doxorubicin and SNAI2 down-regulation sensitized DU145 cell line to chemotherapeutic drugs by increasing PTEN expression." (PMID 27760172, 2016). "SNAI2 has been identified as a target gene of miR-203 in breast and prostate cancer, and we confirmed that mature miR-203 decreased the relative luciferase activity of the 3′-UTR reporter vectors by approximately 50-70%." (PMID 26882562, 2016). "Transcriptome profile showed that RUNX2 was associated with the malignant behavior of prostate cancer, including invasion and bone spread by up-regulating MMP9, SNAI2 and Smad3." (PMID 27007162, 2016).
prostate carcinoma (continued). "Through the analysis of seven datasets (TCGA, GSE30521, GSE4602, GSE55945, GSE69223 GSE104131, and GSE200879), we identified two upregulated genes (AMACR and GCNT1) and seven downregulated genes (TGFB3, SRD5A2, PGM5, HOXD10, AOX1, HSPB6, and SNAI2) in prostate cancer compared to normal tissue." (PMID 38374143, 2024). "In prostate cancer, dynamic expression of SNAI2 could predict tumor progression and drug sensitivity." (PMID 37251370, 2023). "Furthermore, SNAI2 has a major influence on the tumor microenvironment by reactivating tumor stroma and creating an immunosuppressive microenvironment in prostate cancer." (PMID 34792282, 2022). "One study has testified that SNAI2 silence could extremely impede the proliferation metastasis and stemness of prostate cancer cells." (PMID 34966442, 2021). "SNAI2 gene expression is often downregulated due to methylation of the promoter; the expression of SNAI2 is restored or elevated at the invasion front of high-grade prostate cancer and lymph node metastases." (PMID 31060254, 2019). "However, mRNA expression of SNAI2 (Slug), showed significant downregulation in metastatic prostate cancer tissues compared to the primary tumor group." (PMID 31060254, 2019). "Thus, we identified the most significant model of three-gene signature (CDK4, TWIST1, and SNAI2) that was able to predict the survival of prostate cancer patients for the first time." (PMID 31060254, 2019). "Therefore, we conclude that both PCAT3 and PCAT9 form a reciprocal repression regulatory loop with miR-203 to regulate prostate cancer proliferation and progression by modulating SNAI2 expression." (PMID 29552304, 2018). "In PCa, SNAI2 promotes prostate cancer xenograft growth via modulating Cyclin D1." (PMID 29552304, 2018). "This study revealed that EBAG9 modulates the expression of EMT-related genes containing VIM, SNAI1, and SNAI2 in prostate cancer cells, suggesting that EBAG9 could stimulate cancer progression and invasion through EMT pathway." (PMID 29362448, 2018). "Indeed, silencing of GPR137 resulted in a downregulation of SNAI1/SNAIL and SNAI2/SLUG and a corresponding increase in E-cadherin expression in human prostate cancer cells." (PMID 28975893, 2017). "Among different subgroups in prostate cancer scRNAseq data, significant correlations between EMP1/COL3A1 and four EMT genes (VIM, SNAI2, TWIST1, and CTNNB1) were found in the osteoblast subgroup." (PMID 38187400, 2023). "Three GEO datasets were identified when the 1KB domain of the SNAI2 TSS was investigated for potential VDR binding in lymphocytes, hepatocytes, and prostate cancer cells." (PMID 37228489, 2023). "Collectively, these results indicated that there was low expression of CCND1, CDK4 and TWIST1; high expression of SNAI1, SNAI2, and CDH1 was correlated with good prognosis of prostate cancer patients." (PMID 31060254, 2019). "We found that depending on age of prostate cancer patients and Gleason score EMT genes with distinctly altered expression are: KRT18, KRT19, MUC1 and COL4A1, CTNNB1, SNAI2, ZEB1 and MMP3." (PMID 29206234, 2017). "Integrative clinical data from 18 prostate cancer cohorts and experimental evidence showed that gene fusion between transmembrane serine protease 2 (TMPRSS2) and ETS transcription factor ERG (ERG) (TMPRSS2–ERG fusion) is involved in the silencing of SNAI2." (PMID 34792282, 2022). "Also the downregulation of SNAI2, ITGA3, BCL2, PGR, IGFPB3 and HOXD10 was previously reported for prostate cancer." (PMID 28005952, 2016). "In prostate cancer miR-203 exists in a double negative feedback loop with the EMT transcription factor SNAI2, along with ZNF217 and miR-203 was previously shown to differentiate EAC from BE and decreased expression associated with poorer EAC patient outcome." (PMID 27363029, 2016).
prostate carcinoma (continued). "Snai2 is enriched in basal prostate stem cell (mPSC) populations, and the increased organoid formation capacity of mPSC Snai2+ populations mediates TMPRSS4-induced increases in SOX2 and ALDH activity and the acquisition of CSC-like signatures in prostate cancer." (PMID 40919166, 2025). "The link between SPINK1 and increasing sphere formation ability in prostate cancer was also validated using the 22RV1 cell line and by regulating the expression of genes involved in stemness and epithelial-mesenchymal transition (EMT), including SNAI1 (SNAIL), SNAI2 (SLUG), and TWIST1." (PMID 33916984, 2021). "However, the cross-talk among lncRNAs, miRNAs and SNAI2 in the formation and progression of prostate cancer has not been reported." (PMID 29552304, 2018).